TFRC (transferrin receptor)
Diseases named in the same sentence as TFRC in open-access papers (continued):
Sharing a sentence is not in itself a finding about the gene and the disease.
tumor (continued). "Most FRGs with gain of CNV exhibited significantly higher expression in BCa tumor tissues compared to normal adjacent tumor tissues or normal bladder tissues, such as FANCD2, EMC2, and TFRC." (PMID 35386202, 2022). "The transferrin receptor (TfR) contributes to iron import and a higher TfR concentration has been found in CLL directly reflecting the large tumor burden." (PMID 35761419, 2022). "Therefore, we speculated that TFRC might have a dual role in regulating tumor progress." (PMID 36483569, 2022). "Transcription of ESR1 gene is subjected to inhibitory autoregulation that was predicted to involve a network consisting of a multifunctional tumour suppressor gene DIRAS3, TGFB1, and transferrin receptor TFRC." (PMID 35218417, 2022). "In agreement with the mixed normal and tumor datasets, PBMC displayed positive correlations between ACE2/TMPRSS2, TMPRSS2/FURIN, ACE2/TFRC, FURIN/TFRC, TMPRSS2/CTSL, FURIN/CTSL, TMPRSS2/MYC, and FURIN/AKT1 and a negative association between ACE2/ADAM17." (PMID 33796097, 2021). "Consistently, MYCN upregulation enhances the protein level of TfR1 in NB cells, which parallels with TFRC levels in NB tumor tissues." (PMID 34011924, 2021). "The validation of the two main pro-oncogenic factors, TFRC and DTL, in an independent tumor sample cohort verifies the developed analysis pipeline and confirms a signature comprising 65 genes of primarily miRNA-dependent transcripts distinguishing ATC." (PMID 34885022, 2021). "We found that while TFRC was poorly expressed, VDAC was highly expressed in tumor tissues compared with normal tissues." (PMID 34093811, 2021). "Mechanistically, TFRC was identified as a direct target of YTHDF1 in HPSCC cells and promoted iron metabolism, thereby increasing tumor growth and proliferation." (PMID 33204330, 2020). "For example, transferrin receptor 1 (TFR1) is involved in the regulation of iron uptake and cell growth, is abnormally expressed in tumors and is closely related to tumor proliferation and metastasis." (PMID 33489900, 2020). "AS1411, which binds nucleolin and induces tumor cell apoptosis, and GS24, which binds the transferrin receptor (TRF), helped to pass the BBB." (PMID 32764266, 2020). "Western blot analysis also further demonstrated ~1.4-fold increased expression of transferrin receptor in U87MG compared to GL261 cells, consistent with the relative differences in staining intensity observed between tumor types on IHC." (PMID 29777137, 2018). "Retro-Tf-D-LP4, containing the human transferrin receptor (TfR)-recognition sequence, crossed the blood-brain barrier (BBB) via the TfR that is highly expressed in the BBB to strongly inhibit tumor growth in an intracranial xenograft mouse model." (PMID 28412744, 2017). "In contrast, the level of miR-152 was markedly reduced in HCC tissue samples, with the values being significantly lower at each tumor stage of HCC progression, and inversely correlated with the TFRC expression (p = 0.0078)." (PMID 26657500, 2016). "After the tumors reached a size of 150 mm3, the anti-TFRC antibody or PBS (control) was intravenously injected twice per week for 3 weeks, and the tumor growth and weight were monitored at each time point." (PMID 24890018, 2014). "Relationship between transferrin receptor (TFR), ABCB6, and ABCB7 mRNA expression and response to artesunate (ART) in tumor cell lines of the NCI drug screening panel." (PMID 17726528, 2007). "The transferrin receptor was found on similar numbers of CD8+ T cells in peripheral blood and among the tumour infiltrating lymphocytes while more of the CD4+ T cells infiltrating the tumour were found to carry this receptor (P = 0.034)." (PMID 2124138, 1990). "Similarly, the transferrin receptor, which is overexpressed in many cancers including HCC, has been utilized to improve nanoparticle uptake by tumor cells." (PMID 39776807, 2025).
tumor (continued). "The downregulation of TFRC leads to reduced iron transport, and the low expression of ACSL4 impairs the catalysis of the substrates necessary for the formation of lipid hydroperoxides, thereby reducing ferroptosis-mediated cell death in tumor cells." (PMID 41011250, 2025). "TFRC and CALU may help tumor cells cope with metabolic stress, such as ferroptosis and endoplasmic reticulum stress." (PMID 41595468, 2025). "Iron-dead PMN-MDSCs highly express CD71 (transferrin receptor 1) on their surface, which transmits inhibitory signals through interactions with T cells and releases TGF-β and oxidized lipids, synergistically suppressing anti-tumor immunity." (PMID 40535125, 2025). "The inhibition of TFRC, which inhibited iron uptake, significantly decreased cell survival in both lung (A549) and breast (MDA-MB-231) cancer cells, indicating that iron is critical for tumor cell survival." (PMID 40897687, 2025). "For example, a hypoxic tumor micro-environment can mediate tumor cell ferroptosis resistance by activating HIF1α and upregulating various anti-ferroptosis molecules such as SLC7A11, GPX4, TFRC and FTH115-17." (PMID 41049011, 2025). "RT-qPCR confirmed that MMP1, TFRC, and CXCL8 were upregulated in tumor tissues." (PMID 40809844, 2025). "TFRC was significantly higher expressed in BLCA tumor samples compared with normal samples, and survival curves showed BLCA patients with low TFRC expression level had significantly longer OS compared with that with high TFRC expression level." (PMID 38336764, 2024). "Many primary and metastatic tumor cells overexpress regulatory peptides, such as human epidermal growth factor receptor (HER-2), gonadotropin-releasing hormone receptor (GnRH-R), transferrin receptor (TfR), etc., to varying degrees." (PMID 38399294, 2024). "External immunohistochemical analysis showed that TFRC and SLC7A11 were highly expressed in tumor tissues compared with para-cancer normal tissues, and the expression level was significantly associated with a more advanced stage and worse cancer-specific survival." (PMID 37940859, 2023). "TFRC protein has been shown to regulate the progression of several squamous epithelial tumours, however, no functional analysis has been performed on the ability of NCBP2 to regulate tumour progression." (PMID 36635327, 2023). "Expression of NCBP2 and TFRC is significantly higher in tumour cells compared to most normal human tissues." (PMID 36635327, 2023). "Interestingly, our single-cell RNAseq analysis revealed significant expression of TFRC in dendritic cells and macrophages, whereas NCBP2 expression was almost entirely restricted to tumour cells." (PMID 36635327, 2023). "The TIDE algorithm showed that elevated expression of TFRC was related to high TIDE scores, suggesting tumor immune dysfunction and exclusion may occur." (PMID 36483569, 2022). "This scL53 nanocomplex can be specifically delivered to tumors based on the tumor transferrin receptor that is not expressed on normal cells." (PMID 35454137, 2022). "However, the transferrin receptor (TfR) is a more particularly relevant target, as it is overexpressed in the GBM tumor cells and also in the BBB." (PMID 35214012, 2022). "In the Shantou cohort, the result showed that the TFRC protein expression in the high-grade group of LGG was higher than those in the low-grade group, and the spatial distribution of TFRC was mainly in tumor cytoplasm and blood vessels by the immunohistochemical method." (PMID 36483569, 2022). "The results showed that TFRC mRNA expression in HCC patients was positively related to the relative percent of tumor-infiltrating M2 macrophages but not M1 macrophages." (PMID 34389031, 2021). "Collectively, we identified iron starvation through TFRC-mediated iron competition drives functional immunosuppressive polarization of TAM, providing new insight into the interconnection between iron metabolism and tumor immunity." (PMID 34389031, 2021).
tumor (continued). "Here, we report the novel dual-targeting ruthenium candidate 2b, which has both antitumor and antimetastatic properties and targets tumor sites through the enhanced permeability and retention (EPR) effect and transferrin/transferrin receptor (TF/TFR) interaction." (PMID 33892746, 2021). "Our results distinguished FASN, FN, TFRC and TSC1 from previously identified tumour promoters and revealed novel prediction model IPRPs that outperformed the currently established prognostic parameters for anticipating disease course and better clinical management of adult ACC." (PMID 33626208, 2021). "In addition, our studies unraveled the upregulation of major pro-oncogenic drivers in ATC such as the E3-ubiqutin ligases DTL promoting the decay of tumor suppressors such as PDCD4 and the transferrin receptor TFRC (CD71)." (PMID 34885022, 2021). "Transferrin receptor one (TFR-1), recognized by ferritin, is overexpressed in many tumor cells." (PMID 33809013, 2021). "To determine whether TFRC expression correlated with HCC immune microenvironment, we algorithmically analyzed the diversity and landscape of 22 tumor-infiltrating immune cells using the CIBERSORT database." (PMID 34389031, 2021). "Moreover, TFRC overexpression phenocopies MYCN amplification to increase the intracellular iron pool and sensitize these tumor cells to ferroptosis." (PMID 34011924, 2021). "As the tumor grade increased, DPP4, HMOX1, and TFRC expression levels also increased." (PMID 35154262, 2021). "Tumor cells increase iron uptake through the upregulation of divalent metal transporter-1 (DMT1), transferrin/transferrin-receptor (Tf/TfR), and lipocalin-2/lipocalin-2receptor (Lcn-2/Lcn-2R) systems, and its storage by ferritin (FT) heavy chain (FTH) and FTL overexpression." (PMID 32426284, 2020). "Alternatively, transferrin-bound iron may be taken up via the transferrin receptor 1 (TFRC1), which is highly expressed in tumor cells." (PMID 31383898, 2019). "This increased uniform staining for the transferrin receptor throughout the tumor was not seen in serial sections stained using control IgG antibody (IgG Control)." (PMID 29777137, 2018). "Additionally, using the TCGA database, we demonstrated an over-expression of TFRC in human HCC tissue samples and a markedly decreased level of microRNA-152 (miR-152) when compared to non-tumor liver tissue." (PMID 26657500, 2016). "On the other hand, tumor cells that express low levels of the transferrin receptor, and other structures within the intra-cranial cavity do not show any significant binding to test platelets." (PMID 27049725, 2016). "Moreover, glutamate release from cancer cells is mediated by TFRC which makes GBM cells exotoxic for neurons and provides space for the progression of tumor mass." (PMID 25356585, 2014). "Notably, CALU, TFRC, and GBP2 were highly expressed in early developmental stages, whereas SERPINB5 and LY6D were up-regulated in later phases, indicating their involvement in distinct stages of cellular state transitions and tumor progression." (PMID 41595468, 2025). "In contrast, this study identified a distinct circRNA isoform, hsa_circ_0068608 (circTFRC), spanning exons 2–18, which exhibited elevated expression in GC and independently influenced ferroptosis and tumor development, without reliance on either TFRC mRNA or hsa_circ_0068631." (PMID 40473597, 2025). "Moreover, leveraging transferrin receptor-mediated delivery pathways, as evidenced in brain delivery and cancer targeting studies 64, 65, suggests that oAd5/3-TBD-GFP may enhance tumor selectivity." (PMID 39816694, 2025). "Therefore, we first evaluated the effect of LASS2 on the TFRC protein level in multiple tumour cell lines with or without treatment with a ferroptosis inhibitor (Fer-1) treatment or a ferroptosis agonist (erastin)." (PMID 38419028, 2024).
tumor (continued). "Mechanistically, anlotinib suppresses the expression of TFRC by inhibiting the VEGFR2‐AKT‐HIF axis, which in turn enhances the secretion of CXCL14 and recruits tumour‐infiltrating CD8+ T cells, particularly PD‐1+CD8+ T cells, thereby potentiating the anti‐tumour efficacy of anti‐PD‐1 treatment." (PMID 39095323, 2024). "In the orthotopic xenograft tumor mouse models established with PDX cell lines, animals subcutaneously implanted with PDX-vector-shSOX9/SOX2/OCT4-shFTH1/FTL/TFRC or PDX-c-Jun-OE-shSOX9/SOX2/OCT4-shFTH1/FTL/TFRC cell lines exhibited comparable tumor burdens and tumor weights after GEM treatment." (PMID 37143164, 2023). "Knockdown of TFRC using two siRNA to investigate the effects on intracellular iron level and biological functions, including proliferation by CKK-8 assay, colony formation, cell apoptosis and cell cycle by flow cytometry, migration and invasion, and tumor growth in vivo by nude mouse xenografts." (PMID 37644594, 2023). "Finally, we did not analyze the expression levels of TFRC in other tumor cells after treatment with related drugs, especially in solid tumors." (PMID 37041636, 2023). "Similarly, tumor cells are “addicted” to iron because they have decreased expression of ferroportin (FPN), the iron efflux pump, and overexpress the transferrin receptor (TfR1), the iron importer." (PMID 35898880, 2022). "However, while tumor localization is an encouraging proof of concept, since Waz does not cross react with the murine transferrin receptor, additional studies are required to better understand its targeting capability in more realistic systems." (PMID 34725326, 2021). "In this system, tumor-targeting aptamer (FB4, an RNA aptamer specifically binding to the extracellular domain of a transferrin receptor expressed by MCF-7 cells) could deliver siRNA into the target cells through aptamer-mediated endocytosis in a specific and efficient manner." (PMID 30943985, 2019). "Apparently, the expression of different iron-regulated genes such as the transferrin receptor (TfR1), ferritin light chain (FTL), and the iron regulatory protein (IRP)-2 in tumor cells correlated with a poor prognosis, a higher tumor grade, and increased chemoresistance." (PMID 30641920, 2019). "Moreover, the expression of different iron-regulated genes such as transferrin receptor (TfR), ferritin light (FTL), and the iron regulatory protein (IRP)-2 in tumor cells was correlated with a poor prognosis and a higher tumor grade, leading to increased chemoresistance." (PMID 27806101, 2016). "This suggestion is supported by the findings of the present study and by a recent report demonstrating an up-regulation of TFRC in human HCC samples as compared to adjacent not-tumor tissue and that TFRC over-expression was significantly associated with serum levels of α-fetoprotein." (PMID 26657500, 2016). "Additionally, it has been demonstrated that the IRP2 binding activity is selectively activated by low iron, positively correlated with a TFRC expression, and the induction of IRP2 promoted tumor growth, while up-regulation of IRP1 exhibited a tumor suppressive effect." (PMID 26657500, 2016). "Here, we showed that the TFRC expression level is a candidate tumor marker for OSCC development from dysplasia and that TFRC itself could possibly be a therapeutic target for OSCC with the development of the anti-human TFRC-specific antibody described in this manuscript." (PMID 24890018, 2014). "The stimulation was inhibited by the GB16 antibody to the transferrin receptor, but increased transferrin receptor in tumor cells does not necessarily increase stimulation which indicates that the transferrin receptor itself is not alone sufficient to act as an oxidase." (PMID 22400117, 2012).
tumor (continued). "The novel drug is based on poly(β-L-malic acid) (PMLA) platform, which is non-toxic, non-immunogenic, biodegradable, and is a tumor specific drug delivery system with covalently conjugated anti-transferrin receptor (TfR) mAb for transcytosis across the endothelial system." (PMID 22355336, 2012). "However, it is not clear whether the ferroptosis-related molecule TFRC affects tumor immunity in LGG." (PMID 36483569, 2022). "mRNA levels of transferrin receptor 1 (TFR1 or CD71) are tightly negatively regulated by biologically active intracellular iron and, thus, cell surface levels of the protein may be used as a sensitive surrogate marker for gauging iron availability in the tumor microenvironment." (PMID 33344239, 2020). "It is a proprietary nanoparticle formulation targeted at the transferrin receptor, containing non-chemically modified small interfering RNA (siRNA) against the M2 subunit of ribonucleotide reductase (RRM2), with potential anti-tumor activity." (PMID 39968416, 2025). "Meanwhile, TFRC expression was correlated with HPV infection status, the expression of TFRC in tumor with HPV16 was significantly higher than that in non-malignant with HPV16 (p < 0.05)." (PMID 40303995, 2025). "Strong immunoreactivity of TFRC, LAMC1, PLK1, and TYMS was observed in tumor tissues, whereas weak or no staining was observed in normal tissues." (PMID 40496862, 2025). "Transferrin receptor-1 and ACSL4 increased slightly in the neratinib-treated group but were not significantly different from control tumours." (PMID 31409375, 2019). "In this study, we have found an association between the expression of the follow proteins (STAT5, STAT3_pS727, BMP6, CD74, TFRC, INHA, and STAT5_pY694) involved in iron homeostasis and the type of tumor tissue (breast cancerous vs. non-cancerous)." (PMID 28216608, 2017).